LBP (lipopolysaccharide binding protein)
Diseases named in the same sentence as LBP in open-access papers (continued):
Sharing a sentence is not in itself a finding about the gene and the disease.
Hyperglycemia (3 papers, 2017 to 2024). An increased concentration of glucose in the blood. "In estrus synchronized post-pubertal pigs, LPS exposure for the duration of the follicular phase increased circulating insulin and elevated LPS binding protein (LBP), serum 17β-estradiol (E2), and hyperglycemia." (PMID 39401133, 2024). "In addition, as hyperglycemia suppresses the function of macrophages, impaired glycemic control might reduce the clearance of LPS from blood and consequently contribute to higher plasma LBP levels." (PMID 31536546, 2019).
Hypertension (3 papers, 2018 to 2023). The presence of chronic increased pressure in the systemic arterial system. "In a study of 441 community-dwelling adults, Cuesta-Zuluaga claimed that individuals with higher butyrate excretion have fewer lipopolysaccharide-binding protein (LBP) level and is associated with hypertension." (PMID 36035928, 2022).
influenza (3 papers, 2016 to 2025). An acute viral infection of the respiratory tract, occurring in isolated cases, in epidemics, or in pandemics; it is caused by serologically different strains of viruses (influenzaviruses) designated A, B, and C, has a 3-day incubation period, and usually lasts for 3 to 10 days. "In addition, SYR treatment reduced the serum level of lipopolysaccharide-binding protein, an inflammatory marker, and enhanced humoral immunity against influenza vaccination to the level of young control mice." (PMID 27976725, 2016). "LBP and SERPINA3 were mainly elevated in lung damage induced by influenza and non‐COVID‐19 DAD." (PMID 37519267, 2023).
kidney transplant (3 papers, 2019 to 2025). A surgical procedure in which one or both kidneys from a donor are implanted into a recipient. "In conclusion, we discovered and validated urinary exosomal proteins LBP and CST3 as potent non-invasive biomarkers for ABMR in kidney transplant recipients." (PMID 36289608, 2022). "In addition, GGM was demonstrated to significantly increase the serum levels of butyric acid and caproic acid while lipopolysaccharide binding protein (LBP) concentrations, thereby contributing to relieving the LUTS of prostatitis." (PMID 40143861, 2025). "Particularly, we discovered and validated urinary exosomal proteins CST3 and LBP, which could be combined to serve as a potent composite biomarker of ABMR in kidney transplant recipients." (PMID 36289608, 2022).
liver inflammation (3 papers, 2016 to 2023). "Within the subgroup of patients with circulating LBP concentration below the median value, 77.3% had liver inflammation, whereas this prevalence dropped to 48% among individuals with upper median LBP levels." (PMID 38139003, 2023). "LPS and LBP levels did not correlate with plasma AST levels, liver inflammation, NAS or fibrosis scores nor did they correlate with waist-to-hip ratio." (PMID 27992443, 2016).
malnutrition (3 papers, 2016 to 2025). Inadequate nutrition resulting from poor diet, malabsorption, or abnormal nutrient distribution. "This study aimed to assess plasma levels of LBP and inflammatory biomarkers in SARS-CoV-2 patients with different malnutrition status and severity levels." (PMID 40565820, 2025).
mental disorder (3 papers, 2019 to 2024). A disease that has its basis in the disruption of mental process. "The involvement of calprotectin, zonulin, LBP and IFABP/FABP2 in the study of mental disorders remains an open matter, given that inflammatory processes are known to be involved in the aetiology of affective disorders." (PMID 36079050, 2022). "The first model (Model-1), including butyric acid, LBP/CD14, and in addition age, testosterone, cortisol, healthy food servings, and psychiatric disorders, explained 47% of BMI variability (adjusted R2 = 0.47)." (PMID 31491976, 2019).
metastatic disease (3 papers, 2021 to 2025). "Biopsies collected from patients with local disease showed 77 % of positive anti-LBP immunoreactivity contrasting to patients with metastatic disease who had only 39 % of biopsies positive to LBP." (PMID 35990515, 2022). "Elevated expression of miR-320a, miR-622, and let-7f-5p, together with increased plasma exosomal levels of lipopolysaccharide-binding protein (LBP), has been significantly correlated with metastatic disease." (PMID 41373464, 2025).
periodontal disease (3 papers, 2011 to 2021). "We measured the level of LBP in the mice serum in order to detect another potential route of periodontal disease (HFD gut dysbiosis-LPS/TLR4 pathway-gingival blood flow-periodontal disease)." (PMID 33746772, 2021).
prediabetes (3 papers, 2021 to 2025). "Current research has identified multiple proteins in serum that are related to the occurrence and development of prediabetes, including C-reactive protein, lipopolysaccharide-binding protein, among others." (PMID 37964953, 2023). "Among Danes, individuals with prediabetes had significantly (Wilcoxon test, padj < 0.05) higher levels of interleukin 6 (IL6), tumor necrosis factor α (TNFα), lipopolysaccharide-binding protein (LBP), and intestinal alkaline phosphatase (IAP) compared to normoglycemic individuals." (PMID 33658065, 2021).
renal failure (3 papers, 2014 to 2024). "Up to 40% cirrhotic patients show circulating bacterial DNA and elevated levels of lipopolysaccharide binding protein as markers of clinically inapparent bacterial translocation from the intestine, which is thought to render patients more susceptible to renal failure." (PMID 25983746, 2015). "Considering that renal fibrosis is pivotal in the development of renal failure, we hypothesize that a selective removal of LBP might represent a future therapeutic strategy with a significant impact on short- and long-term outcomes for patients with LPS-induced AKI." (PMID 25261195, 2014).
Shock (3 papers, 2009 to 2018). The state in which profound and widespread reduction of effective tissue perfusion leads first to reversible, and then if prolonged, to irreversible cellular injury. "LBP is an acute phase protein that is upregulated in response to many stimuli (BDL, hemorrhagic shock, and infection)." (PMID 30525057, 2018).
acute liver failure (2 papers, 2015 to 2025). Rapid deterioration of liver function causing encephalopathy and coagulopathy. "In patients with ACLF grade 2/3, we here observed even lower levels of circulating LBP despite increasing levels of CRP as in acute liver failure." (PMID 40317887, 2025).
acute pancreatitis (2 papers, 2023 to 2024). An acute inflammatory process that leads to necrosis of the pancreatic parenchyma. "Concentrations of LBP have been found to be significantly elevated in patients suffering from severe acute pancreatitis indicating the process of TLR4 signaling may have a role in systemic complications associated with severe acute pancreatitis." (PMID 38585277, 2024). "In contrast to antibiotic decontamination, supplementation of butyrate in KD-fed mice with acute pancreatitis resulted in enhanced integrity of the intestinal barrier, significantly reduced pancreatic tissue necrosis and serum LBP levels, and attenuated oxidative stress in pancreatic tissue." (PMID 37892502, 2023). "Interestingly, although serum LBP level did not significantly increase in KD-fed mice, it exhibited a more pronounced elevation compared with the SD group in the acute pancreatitis model." (PMID 37892502, 2023).
Alzheimer disease (2 papers, 2023 to 2024). A progressive, neurodegenerative disease characterized by loss of function and death of nerve cells in several areas of the brain leading to loss of cognitive function such as memory and language. "Low serum iron has been reported in patients with Alzheimer’s disease compared to healthy subjects, and low serum iron that is correlated with plasma LBP concentration may lead to decreased brain function." (PMID 36837869, 2023). "The role of lipopolysaccharide binding protein (LBP), an inflammation marker of bacterial translocation from the gastrointestinal tract, in Alzheimer’s disease (AD) is not clearly understood." (PMID 38882697, 2024).
anemia (2 papers, 2023 to 2024). A reduction in the number of red blood cells, the amount of hemoglobin, and/or the volume of packed red blood cells. "Here, we found an enhancement of both LBP and sCD14 after mouse infection with Plasmodium yoelii, at the early phase of increased parasitemia and anemia, although this parasite is not supposed to alter the gut barrier." (PMID 37240201, 2023).
Anorexia (2 papers, 2018 to 2022). Lack of desire to eat (loss of appetite). "Increases in cecal Enterobacteriaceae, plasma LBP and hepatic markers of TLR activation were not the consequence of the decreased food intake and anorexia." (PMID 29719601, 2018).
coagulopathies (2 papers, 2018). "These coagulopathies are accompanied by augmented LPS-binding protein (LBP) levels." (PMID 30466424, 2018).
fibrosis (2 papers, 2013 to 2016). the formation of excess fibrous connective tissue in an organ or tissue in a reparative or reactive process. "For both LBP and sCD14, there was a statistically significant difference between the fibrosis groups (p<0.05)." (PMID 23750224, 2013).
gingivitis (2 papers, 2021 to 2026). A disorder involving inflammation of the gums; may affect surrounding and supporting structures of the teeth. "Serum sCD14 and LBP levels (markers of epithelial integrity) increased in the gingivitis phase, and sCD14 remained high after the recovery phase on day 42 (p < 0.05)." (PMID 42125961, 2026).
hepatitis B (2 papers, 2020 to 2023). "Besides, the gene expression of LBP was significantly associated with poor overall survival in patients with hepatitis B virus (HBV) infection." (PMID 32793465, 2020). "The prediction models incorporated zonulin, LPS, LBP, C-reactive protein, age, and history of hepatitis B for AKI, and zonulin, LPS, LBP, total bilirubin, and Child–Pugh score for HRS–AKI." (PMID 37567912, 2023).
injury (2 papers, 2009 to 2022). Damage inflicted on the body as the direct or indirect result of an external force, with or without disruption of structural continuity. "ConA-induced acute liver injury caused a significant increase in the concentration of LBP in the WT+ConA group compared to the WT+NS group." (PMID 35972273, 2022).
liver dysfunction (2 papers, 2015 to 2024). "In this case, liver dysfunction caused by a zonulin-dependent increase in gut permeability leads to decreased synthetic liver function and decreased LBP formation." (PMID 38792318, 2024). "Additionally, as cells residing in the liver (hepatocytes/kupffer cells) contribute to production of sCD14 and LBP the associations between the plasma levels of above markers and fibrosis / liver dysfunction status should further be studied." (PMID 25785448, 2015). "This correlation is related to the formation of LBP in the liver, so liver dysfunction promotes the decreased production of LBP and other proteins, and increased biochemical markers of liver damage." (PMID 38792318, 2024).
meningitis (2 papers, 2013 to 2018). A disorder characterized by acute inflammation of the meninges of the brain and/or spinal cord. "In a murine meningitis experimental model, LBP was able to recognize peptidoglycan breakdown products derived from S. pneumoniae and modulate the inflammatory response." (PMID 24391897, 2013).
peritonitis (2 papers, 2015 to 2021). Inflammation of the peritoneum (tissue that lines the abdominal wall and covers most of the organs in the abdomen). "AMPs have been investigated in patients with abscesses, peritonitis, or uninfected body fluid levels of the LPS-binding protein (LBP) and BPI, which prevents endotoxin binding to CD14." (PMID 26347737, 2015). "LBP suppresses the levels of serum TNF-α and IL-6 in LPS-treated mice peritonitis." (PMID 34884814, 2021).
respiratory failure (2 papers, 2022 to 2025). The significant impairment of gas exchange within the lungs resulting in hypoxia, hypercarbia, or both, to the extent that organ tissue perfusion is severely compromised. "During hospitalization, elevated levels of lipopolysaccharide-binding protein (LBP) in patients’ blood plasma were directly correlated with respiratory failure, defined as pO2/fiO2 < 26.6 kPa." (PMID 36144365, 2022).
sarcopenia (2 papers, 2011 to 2023). Progressive decline in muscle mass due to aging which results in decreased functional capacity of muscles. "Contrary to our expectations, stool zonulin, stool calprotectin and serum LBP, sCD14, IGF‐1, myostatin, FGF‐21, irisin and DAO were comparable in cirrhotic patients with and without sarcopenia and in controls with and without sarcopenia (P > 0.05)." (PMID 37767786, 2023).
septic shock (2 papers, 2013 to 2025). Shock caused by infection; frequently caused by gram negative bacteria, although some cases have been caused by other bacteria, viruses, fungi, and protozoa; characterized by fever, chills, tachycardia, tachypnea, and hypotension. "During an acute-phase reaction, such as septic shock, the LBP concentration can rise 10- to 50-fold and inhibit LPS-induced inflammation, possibly by transferring LPS to lipoproteins." (PMID 23704966, 2013).
synovitis (2 papers, 2021). Inflammation of a synovial membrane. "In sum, this study indicated that WB had obvious inhibitory effects on synovitis of CIA rats, and the mechanisms of which may be involved in downregulating the expression levels of several key proteins including MMP3, MMP19, LBP, IRAK4, and ARPC5." (PMID 34708132, 2021).
type 1 diabetes (2 papers, 2021 to 2024). "In the current study, we aimed to investigate possible associations between gut related inflammatory biomarkers including LBP, CD14, TLR4, I-FABP and IL-18 and the presence of CAD and with established CHD, in patients with long-term type 1 diabetes compared to a control group." (PMID 39563343, 2024). "Interestingly, the findings in our present study did not reveal significant differences in LBP, sCD14 or related substances in the TLR pathway between type 1 diabetes individuals with and without CAD or established CHD." (PMID 39563343, 2024).
age-related macular degeneration (1 paper, 2016). Age-related loss of vision in the central portion of the retina (macula), secondary to retinal degeneration. "The 8 known pQTLs along with the kallikrein pQTL are associated with a variety of phenotypes, including age-related macular degeneration (C3b), activated partial thromboplastin times (F12), serum metabolites (KLKB1), binding of LBP to lipopolysaccharide (LBP), and plasma plasminogen levels (LP(a))." (PMID 27329291, 2016).
alcoholic cirrhosis (1 paper, 2015). "Plasma LBP was higher in AH patients (mean 29 μg/mL) than in alcoholic cirrhosis (mean 17 μg/mL; p < 0.002) and healthy controls (mean 15 μg/mL; p < 0.002)." (PMID 26343741, 2015).
allergic asthma (1 paper, 2019). A asthma with a basis in a pathological type I hypersensitivity reaction. "In particular the human LPS-binding protein (LBP) has been assigned a role in the development of allergic asthma in this context." (PMID 30837983, 2019).
amyloidosis (1 paper, 2023). A disorder characterized by the localized or diffuse accumulation of amyloid protein in various anatomic sites. "Among these processes, breast involution, which resembles the wound healing process, and amyloidosis have been studied, with LBP showing amyloidogenic capacity." (PMID 36982287, 2023).
Anxiety (1 paper, 2021). Intense feelings of nervousness, tension, or panic often arise in response to interpersonal stresses. "High levels of stress were associated with elevations of soluble CD14, lipopolysaccharide binding protein (LBP), and tumor necrosis factor–α, while anxiety was associated with elevated concentrations of C-reactive protein (CRP) in otherwise healthy pregnancies." (PMID 33301421, 2021).
Arthritis (1 paper, 2021). Inflammation of a joint. "Increased levels of serum LBP were observed in mice at early stages of disease and in mice with established arthritis compared to CTRL and pre-disease mice." (PMID 34296202, 2021). "Mice in the acute phase of arthritis showed increased levels of serum LBP and FITC-dextran and decreased epithelial ZO-1 expression compared to naive mice." (PMID 34296202, 2021).
atherosclerotic heart disease (1 paper, 2021). "The LPS/LBP complex is considered a key inflammatory trigger for monocytes and macrophages and has been found to be increased in obese subjects with atherosclerotic heart disease, among whom nLDL is also increased." (PMID 34439835, 2021).
Atherosclerotic lesion (1 paper, 2021). A lesion associated with atherosclerosis, a multifactorial and multipart progressive disease manifested by the focal development within the arterial wall of lesions, that ranges from the development of a fatty streak, plaque progression, and plaque disruption. "Besides, they also found that circulating LBP may independently contribute to the presence of carotid plaque and the carotid intima-media thickness, which may indicate that LBP is associated with the development of atherosclerotic lesions." (PMID 34414217, 2021).
babesiosis (1 paper, 2023). Babesiosis refers to a condition caused by microscopic parasites that infect the red blood cells. "Our data also demonstrated an increased abundances of LBP and CD-14 in babesiosis, underlining the importance of the host inflammatory response and a possible modulating effect of LTF." (PMID 37353646, 2023).
Brain atrophy (1 paper, 2025). Partial or complete wasting (loss) of brain tissue that was once present. "Similarly, plasma biomarkers GFAP, IL-17A, and lipopolysaccharide-binding protein (LBP), as well as complement factors D and C5, showed positive correlations with brain atrophy." (PMID 40305176, 2025).
cholestasis (1 paper, 2024). Impairment of the bile flow caused by obstruction within the liver, or outside the liver in the bile duct system. "Importantly, Chemo-GMT mice did not display most signs of LPS-induced cholestasis (increased bile stain, increased LBP, or reduced expression of genes reduced by LPS exposure)." (PMID 39353099, 2024).
chronic kidney disease (1 paper, 2017). Impairment of the renal function secondary to chronic kidney damage persisting for three or more months. "Both markers were not elevated in our cohort of ESRD patients, in contrast to our previous findings, where we found elevated DAO, lipopolysaccharide binding protein and sCD14 levels in chronic kidney disease stage G3-5 patients, HD and PD patients and patients after kidney transplantation." (PMID 29142271, 2017).
conjunctivitis (1 paper, 2021). Inflammation of the conjunctiva of the eye. "In general, animals injected with LPS show increased levels of the LPS-binding protein (LBP) and develop conjunctivitis, diarrhea, lethargy, piloerection, and huddling symptoms." (PMID 34368182, 2021).
dental caries (1 paper, 2023). The decay of a tooth, in which it becomes softened, discolored, and/or porous. "When the concentration of the vitamin D biomarker 25(OH)D3 in serum was lower than 30 ng/mL in patients with dental caries, the levels of secretory immunoglobulin A (sIgA), LPS binding protein (LBP), cathelicidin and total antioxidant activity decreased." (PMID 36782172, 2023).
E. coli infection (1 paper, 2018). "However, depletion of LBP caused sensitization to E. coli infection, as LBP−/− mice showed increased mortality, decreasing bacterial clearance and severe organ damage." (PMID 30525057, 2018).
eczema (1 paper, 2021). "Although LBP and FABP2 did not correlate with eczema, increased bacterial abundance was associated with increased serum FABP2." (PMID 34194728, 2021).
encephalitis (1 paper, 2020). An acute inflammatory process affecting the brain parenchyma. "To evaluate intestinal permeability in encephalitis patients and healthy controls, we quantified the plasma concentrations of D-LA, iFABP, LPS and LBP, which were previously reported as intestinal integrity biomarkers." (PMID 32973805, 2020).